RNU6-1094P (RNA, U6 small nuclear 1094, pseudogene)
Gene: Small nuclear RNA gene on chromosome 3 (96,608,814 to 96,608,917, reverse strand). Ensembl gene ENSG00000199286.
Homologues: Orthologues: chimpanzee U6 (100% identical), macaque U6 (96% identical). Paralogues in human: RNU6-727P (93% identical), RNU6-797P (92% identical), RNU6-11P (91% identical), RNU6-1243P (91% identical), RNU6-24P (91% identical), RNU6-37P (91% identical), RNU6-43P (91% identical), RNU6-97P (91% identical), RNU6-12P (90% identical), RNU6-1309P (90% identical), RNU6-13P (90% identical), RNU6-25P (90% identical), and 1285 more.